MEG3 (maternally expressed 3)
Diseases named in the same sentence as MEG3 in open-access papers (continued):
Sharing a sentence is not in itself a finding about the gene and the disease.
prostate carcinoma (continued). "For example, in prostate cancer, MEG3 inhibits progression by regulating the miR-9-5p/QKI-5 axis." (PMID 38281945, 2024). "For instance, lncRNA MEG3 could hinder prostate cancer progression via modulating miR-9-5p/QKI-5 axis." (PMID 32420340, 2020). "We also demonstrated that overexpression of MEG3 could effectively inhibit the development of PCa through targeting miR‐9‐5p/QKI‐5 axis in prostate cancer." (PMID 30565858, 2019). "Collectively, these results indicated that MEG3 inhibits prostate cancer in vivo." (PMID 30565858, 2019). "Additionally, the interaction between MEG3 and miR-9-5p has been found in prostate cancer, and MEG suppresses prostate cancer progression via mediating miR-9-5p." (PMID 31531526, 2019). "In conclusion, our study showed that MEG3 was a down‐regulated lncRNA in human prostate cancer, and it could regulate miR‐9‐5p/QKI‐5 expression." (PMID 30565858, 2019). "We screened the down‐regulated lncRNA MEG3 in prostate cancer firstly." (PMID 30565858, 2019). "This study was designed to detecting the influences of lncRNA MEG3 in prostate cancer." (PMID 30565858, 2019). "MEG3 decreased significantly in prostate cancer tissues relative to adjacent normal tissues." (PMID 31760932, 2019). "LncRNA MEG3 was a down‐regulated lncRNA in prostate cancer tissues and cells and could inhibit the expression of miR‐9‐5p, whereas miR‐9‐5p down‐regulated QKI‐5 expression." (PMID 30565858, 2019). "In prostate cancer cells, Meg3 promotes apoptosis and acts as a tumor suppressor." (PMID 28423647, 2017). "Moreover, MEG3 played an important role in the molecular etiology of prostate cancer, which suggested the potential application of MEG3 in prostate cancer therapy." (PMID 27634882, 2016). "Among these lncRNAs, MEG3 is affected in many cancer types, including cervical and prostate cancer." (PMID 26305674, 2015). "However, both MEG3 polymorphisms, rs11627993 C>T and rs7158663 A>G, did not appear to affect prostate cancer susceptibility." (PMID 40242248, 2025). "For instance, lncRNA maternally expressed gene 3 (MEG3) has been reported to function as a tumor suppressor in various cancers such as hemangioma, osteosarcoma, and thyroid carcinoma, and it can serve as a ceRNA for miR-9-5p to mediate the progression of esophageal cancer and prostate cancer." (PMID 31531526, 2019). "Hence, lncRNA MEG3 regulated miR‐9‐5p/QKI‐5 axis in prostate cancer." (PMID 30565858, 2019). "Overexpression of MEG3 inhibits the expression of miR-9-5p and then upregulates QKI-5 to inhibit the proliferation, migration and invasion of prostate cancer cells." (PMID 36523500, 2022). "In this study, relied on detecting the down‐regulated lncRNA MEG3 in prostate cancer, the interactions among MEG3, miR‐9‐5p and QKI‐5 were investigated and the influences on prostate cancer were explored subsequently." (PMID 30565858, 2019). "MiR-141 regulated MEG3 expression through repression of EZH2 expression, a subunit of the polycomb repressor complex 2 (PRC2), in prostate cancer." (PMID 29287592, 2017). "The most frequently altered lncRNAs were DLEU1 and DLEU2, followed by MEG3 and MT1DP, both of which had the alteration frequency >2% in 313 TCGA prostate cancer patients." (PMID 26590405, 2016). "Also, MEG3 inhibits the progression of prostate cancer by facilitating H3K27 trimethylation, and MEG3 knockdown attenuates endoplasmic reticulum stress-mediated apoptosis." (PMID 33425489, 2021). "Furthermore, MEG3 facilitates H3K27 trimethylation of EN2 through binding with EZH2, thus suppressing the development of prostate cancer." (PMID 33061817, 2020).
prostate carcinoma (continued). "Overexpressed MEG3 and QKI‐5 could decrease the abilities of proliferation, migration and invasion in prostate cancer cells effectively and increased the apoptosis rate." (PMID 30565858, 2019).
melanoma (29 papers, 2013 to 2025). A malignant, usually aggressive tumor composed of atypical, neoplastic melanocytes. "Overexpression of POU3F3 is associated with increased melanoma cell proliferation, whereas overexpression of MEG3 induces the opposite effect." (PMID 41463281, 2025). "A recent study examined the association between the lncRNA POU3F3 and MEG3 in tissue samples from 60 patients with melanoma." (PMID 41463281, 2025). "Nevertheless, it should be pointed out that the effects of MEG3 need be further investigated on more melanoma cell lines other than A375 cells and the underlying mechanism of MEG3 demands intensive elucidation on promoting A375 cell apoptosis." (PMID 29808164, 2018). "Further analysis validated that the level of miR-499-5p was inversely associated with CYLD level and MEG3 expression in melanoma tissues and cell lines." (PMID 29808164, 2018). "First, the authors confirmed that melanoma tissue has lower MEG3 suppression relative to the surrounding area, and this expression corresponds to the survival rate." (PMID 41463281, 2025). "In a recent study on the involvement of MEG3 in the regulation of melanoma cell behaviour, researchers found that MEG3 overexpression does not significantly alter pathways involving ERK, STAT, and PI3K." (PMID 41463281, 2025). "It is proposed that by driving the overexpression of MEG3, it should be possible to suppress melanoma progression and metastasis." (PMID 40076754, 2025). "Abolfathi and colleagues revealed that curcumin reduces HOTAIR in a glioblastoma cell line, but also increased expression of lncRNA MEG3, a known tumor suppressor in melanoma." (PMID 40282449, 2025). "The analysis of the literature showed that HOTAIR, MALAT1, and H19 are the oncogenic lncRNAs most studied in melanoma, while MEG3 is an important tumor suppressor decreased in this cancer." (PMID 40282449, 2025). "The HGF–c-met pathway operates in an autocrine manner in melanoma and is typically regulated in an inhibitory way by MEG3." (PMID 41463281, 2025). "Knockdown of MEG3 enhanced melanoma metastasis, whereas GA restored MEG3 activity, significantly inhibiting tumor cell invasion and metastasis." (PMID 41311720, 2025). "In in vitro and in vivo murine melanoma models, researchers reported increased MEG3 expression after treatment with gambogenic acid, leading to inhibition of EMT." (PMID 41463281, 2025). "Conversely, knockdown of MEG3 enhances melanoma cell proliferation, migration, and invasion, confirming its inhibitory role." (PMID 41463281, 2025). "In melanoma cells MEG3 is downregulated, miR-208 is overexpressed, and this results in the inhibition of SOX4 transcription." (PMID 40076754, 2025). "Previous studies report the opposite effect that MEG3 inhibit Wnt signaling and the expression of β-catenin in liver cancer cells and malignant melanoma cells." (PMID 36778210, 2023). "Maternally expressed gene 3 (MEG3) lncRNA, on the other hand, is a tumor suppressor downregulated in melanoma and its low expression has correlated with poor prognosis." (PMID 37325482, 2023). "It has been found that re-expression of MEG3 limits EMT-like phenotype in melanoma through upregulation of E-cadherin by targeting miR-21 and miR-499-5p, which negatively regulates tumor suppressor CYLD lysine 63 deubiquitinase." (PMID 37325482, 2023). "One of them is maternally expressed gene 3 (MEG3), which suppresses melanoma proliferation, has a pro-apoptotic activity and its low expression is correlated with poor prognosis for melanoma patients." (PMID 34638331, 2021). "POU3F3 overexpression increased melanoma cell proliferation, while MEG3 overexpression decreased melanoma cell proliferation." (PMID 35201451, 2021). "In this study, we proved that POU3F3 promoted melanoma cell proliferation possibly by downregulating MEG3, a tumor suppressor in melanoma." (PMID 35201451, 2021). "MEG3 enhances the growth, metastasis and formation of melanoma via regulating miR-21 and E-cadherin." (PMID 34247598, 2021).
melanoma (continued). "Cancer susceptibility candidate 2 (CASC2), LINC00961, LINC00459 and maternally expressed gene 3 (MEG3) have been described as tumor-suppressor lncRNAs in melanoma." (PMID 33503876, 2021). "Analysis of CCK-8 assay data showed that POU3F3 overexpression increased melanoma cell proliferation, while MEG3 overexpression decreased melanoma cell proliferation (p < 0.05)." (PMID 35201451, 2021). "In the present study, we proved that POU3F3 plays a role as the upstream inhibitor of MEG3 in regulating melanoma cell proliferation." (PMID 35201451, 2021). "POU3F3 and MEG3 were overexpressed in A375 and M21 cells, two human melanoma cell lines, to further investigate their interactions in melanoma." (PMID 35201451, 2021). "Meanwhile, because of the defects in in vitro experiments, more mechanistic researches and animal experiments are required for better elaborating the detailed role of lncRNA MEG3/miR-21/E-cadherin axis in melanoma." (PMID 31938020, 2020). "In the same study, MEG3 was also found to increase the sensitivity of melanoma cells to cisplatin and 5‐FU treatment." (PMID 33005738, 2020). "Subsequently, based on the differently expressed lncRNA MEG3 and E-cadherin in these human melanoma cell lines, we chose B16, A375 and A2058 cells for the following experiments." (PMID 31938020, 2020). "The results showed that the expression of lncRNA MEG3 was lower in melanoma tissue as compared with their para-carcinoma tissues." (PMID 31938020, 2020). "In the current study, it was also discovered that lncRNA MEG3 presented a declining trend in carcinoma tissues as compared with their para-carcinoma tissues of melanoma." (PMID 31938020, 2020). "In order to further excavate the functions of lncRNA MEG3, we examined the expression of lncRNA MEG3 in different melanoma cell lines and finally selected 3 strains of melanoma cell lines for the following study." (PMID 31938020, 2020). "Moreover, the expression level of lncRNA MEG3 was intimately associated with the survival rate of melanoma, which suggested that lncRNA MEG3 might be served as a prognostic indicator in development of melanoma." (PMID 31938020, 2020). "Based on the different expression of lncRNA MEG3 in human melanoma cell lines, we chose B16 (higher lncRNA MEG3 expression), A2058 (lower lncRNA MEG3 expression) and A375 (lower lncRNA MEG3 expression) cells for the following experiments." (PMID 31938020, 2020). "RT-PCR was used to examine the expressions of lncRNA MEG3 and E-cadherin in melanoma patients and cell lines." (PMID 31938020, 2020). "In conclusion, this report emphasizes that lncRNA MEG3 acts as an antitumor lncRNA for malignant melanoma by regulating miR-21/E-cadherin axis." (PMID 31938020, 2020). "Upregulation of MEG3 inhibited melanoma cell proliferation, invasion, and migration, enhanced melanoma cell apoptosis, and arrested melanoma cell cycle." (PMID 31231466, 2019). "When taken together, these results demonstrate that lncRNA IGF2AS, antiPeg11, MEG3, and Zeb2NAT appear to be independent prognostic factors in BRAF-mutated advanced melanoma patients treated with vemurafenib." (PMID 31231466, 2019). "We show that lncRNA IGF2AS, MEG3, and Zeb2NAT are independent prognostic factors in BRAF-mutated advanced melanoma patients treated with vemurafenib." (PMID 31231466, 2019). "Meanwhile, low expression of MEG3 was positively correlated with poor prognosis in patients with melanoma." (PMID 29808164, 2018). "Collectively, these results concluded that MEG3 played a tumor suppressor role in the tumorigenesis of melanoma." (PMID 29808164, 2018). "The research attempts to explore the effects of MEG3 on the growth and metastasis of malignant melanoma." (PMID 29808164, 2018). "In the report, we confirmed that MEG3 expression was distinctly decreased in 42 of melanoma samples and in melanoma cell lines." (PMID 29808164, 2018).
melanoma (continued). "The effect of MEG3 on growth of melanoma in vivo and cell chemosensitivity was detected by xenograft animal model and CCK-8 assay." (PMID 29808164, 2018). "The combined results identified that MEG3 suppressed melanoma cell proliferation and invasion by regulating the expression of CYLD mediated by sponging miR-499-5p." (PMID 29808164, 2018). "In this research, we confirmed that MEG3 played antitumor role in malignant melanoma development through miR-499-5p/CYLD axis." (PMID 29808164, 2018). "In melanoma models, GA exerted antitumor effects by upregulating lncRNA MEG3." (PMID 41311720, 2025). "In addition, the interaction between POU3F3 and MEG3 characterized in this study provided new insights into the pathogenesis of melanoma." (PMID 35201451, 2021). "We found that POU3F3 was upregulated, while lncRNA MEG3 was downregulated in melanoma." (PMID 35201451, 2021). "Therefore, this study was performed to investigate the crosstalk between POU3F3 and MEG3 in melanoma." (PMID 35201451, 2021). "However, compared to C and NC groups, POU3F3 overexpression decreased MEG3 expression in melanoma cells (p < 0.05), while MEG3 overexpression failed to significantly affect POU3F3 (p < 0.05)." (PMID 35201451, 2021). "Interestingly, a recent study reported that MEG3 inhibited the migration and invasion of melanoma through its interactions with Wnt signaling pathway." (PMID 35201451, 2021). "Then, the biological functions of lncRNA MEG3 and E-cadherin were demonstrated by transfecting lncRNA MEG3-siRNA, lncRNA MEG3-overexpression, E-cadherin-siRNA and E-cadherin-overexpression plasmids in melanoma cell lines." (PMID 31938020, 2020). "Additionally, lncRNA MEG3 was also explored in the development of melanoma, e.g., lncRNAMEG3 suppresses the proliferation and invasion of melanoma by regulating CYLD expression mediated by sponging miR-499-5p." (PMID 31938020, 2020). "Moreover, when changing the expression of lncRNA MEG3 and miR-21 in melanoma cell lines, it was found that miR-21 and E-cadherin both presented a negative alteration, respectively." (PMID 31938020, 2020). "Collectively, the present study helped to reveal that targeting lncRNA MEG3/miR-21/E-cadherin axis may be a promising therapy strategy for melanoma patients." (PMID 31938020, 2020). "Thereby, these results hinted that the E-cadherin expression might play an important role which was intimately related to lncRNA MEG3 in progression of melanoma." (PMID 31938020, 2020). "The results showed that downregulation of the expression of the lncRNA MEG3 promoted melanoma growth, metastasis and formation; thereby it speculated that lncRNA MEG3 might exert a tumor suppressor role in development of melanoma." (PMID 31938020, 2020). "Therefore, in this study, we sought to look at the relationship among lncRNA MEG3, miR-21 and E-cadherin, and further investigate the possible role of lncRNA MEG3/miR-21/E-cadherin regulatory axis in progression of melanoma." (PMID 31938020, 2020). "Additionally, as similar with the expression of lncRNA MEG3 in melanoma cell lines, it was uncovered that the expression of E-cadherin was higher in HEMn and B16 cells than that in A2058 and A375 cells." (PMID 31938020, 2020). "Interestingly, GAS5 seems to repress melanoma tumorigenesis via miR-137, while MEG3 inhibits tumour growth and metastasis by modulating miR-21/E-cadherin axis." (PMID 33203119, 2020). "Our findings indicated that lncRNA MEG3 might inhibit the tumor growth, tumor metastasis and formation of melanoma by modulating miR-21/E-cadherin axis." (PMID 31938020, 2020). "In conclusion, MEG3 has a crucial function in the tumorigenesis of melanoma, and MEG3 may be a potential therapeutic target in the treatment of melanoma." (PMID 29808164, 2018). "For all that, the main function of MEG3 on the development of melanoma remains remarkably obscure." (PMID 29808164, 2018).
melanoma (continued). "The abnormal expression of long noncoding RNA- (lncRNA-) MEG3 was clearly identified in a number of malignant tumors, but the specific function of MEG3 remains unknown in malignant melanoma until now." (PMID 29808164, 2018). "Taken together, CYLD mediated, at least in part, the effect of MEG3 on tumorigenesis of melanoma." (PMID 29808164, 2018). "Functionally, upregulation of MEG3 inhibited melanoma cell proliferation, invasion, and migration, enhanced melanoma cell apoptosis, arrested melanoma cell cycle, and regulated the expression of E-cadherin, N-cadherin, and cyclin D1 by regulating CYLD expression mediated by sponging miR-499-5p." (PMID 29808164, 2018). "A xenograft model was used to further investigate the effect of MEG3 on melanoma in vivo." (PMID 29808164, 2018). "As a result, the expression of MEG3 was decreased in melanoma tissues and cell lines." (PMID 29808164, 2018). "Furthermore, MEG3 was shown to inhibit tumor formation, growth and metastasis in melanoma." (PMID 36009267, 2022). "Moreover, MEG3 levels in tumors decreased with melanoma progressing from stage I to IV (p < 0.05)." (PMID 35201451, 2021). "Finally, MEG3 suppresses proliferation and shows the pro-apoptotic function in melanoma as well." (PMID 33503876, 2021). "POU3F3 may promote melanoma cell proliferation by downregulating MEG3." (PMID 35201451, 2021). "Hence, these findings implied that lncRNA MEG3 suppression might enhance the tumor metastasis and formation of melanoma cell." (PMID 31938020, 2020). "However, the role of lncRNA MEG3 in melanoma has seldom been studied." (PMID 31938020, 2020). "Together, this report emphasizes that MEG3 acts as an antitumor lncRNA for malignant melanoma by regulating miR-499-5p/CYLD axis; MEG3 may be a novel and crucial biomarker in patients with melanoma and can be used as a promising molecular target in the treatment of malignant melanoma." (PMID 29808164, 2018). "Thus, we concluded that overexpression of MEG3 could inhibit melanoma cells growth and reduce cell invasion." (PMID 29808164, 2018). "By sponging miR-499-5p and miR-208, MEG3 is a tumor-suppressor lncRNA that regulates the expression of CYLD and SOX4, inducing a reduction in proliferation and invasion of melanoma cells." (PMID 40282449, 2025). "For instance, lncRNAs PSMG3-AS1 and MEG3 negatively regulate each other, affecting proliferation in endometrial carcinoma cells, while POU3F3 promotes melanoma cell proliferation by suppressing MEG3." (PMID 40350996, 2025). "Three lncRNAs are potential predictive indicators of the effectiveness of vemurafenib therapy in persons with melanoma: IGF2 antisense (IGF2AS), MEG3, along with zinc finger AE-binding homeobox 2-natural antisense transcript (Zeb2NAT)." (PMID 39777348, 2024). "In order to clarify the significance of HOTIAR, MEG3 and TUG1 (family), it would be advisable to conduct an analysis on a large population of melanoma patients and healthy patients, both in tumor tissue and serum." (PMID 38601651, 2024). "Other lncRNAs that inhibit melanoma growth and metastasis dissemination include LINC00961, LINC00459, and MEG3, all acting as miRNA decoys." (PMID 35159386, 2022). "Three of these lncRNAs-IGF2AS, MEG3, ZEB2-AS1—were identified as independent prognostic factors in BRAF-mutant advanced melanoma patient sera treated with vemurafenib." (PMID 35159386, 2022). "Many lncRNAs have been proved to be oncogenes in melanoma, such as FOXD3-AS1, NEAT1, MALAT1 and MEG3." (PMID 34247598, 2021). "Lastly, lncRNAs can also act as tumour suppressors in melanoma, however only growth arrest-specific transcript 5 (GAS5) and maternally expressed gene 3 (MEG3) have been reported so far." (PMID 33203119, 2020). "Further analysis demonstrated that the baseline lncRNAs for IGF2AS, anti-Peg11, MEG3, Zeb2NAT are independent prognostic factors in BRAF-mutant advanced melanoma patients treated with vemurafenib." (PMID 31231466, 2019).